CCL2 (C-C motif chemokine ligand 2)
Diseases named in the same sentence as CCL2 in open-access papers (continued):
Sharing a sentence is not in itself a finding about the gene and the disease.
infection (continued). "Neutrophil CCL2 secretion was significantly higher than monocyte secretion 2 h after infection (P = 0.029 after 2 h; P < 0.001 after 3 h)." (PMID 22058091, 2012). "CCL2 is a chemoattractant protein that recruits monocytes to sites of infection and trauma, and it regulates monocyte, dendritic cell, memory T cell, and basophil infiltration during inflammation." (PMID 21757418, 2011). "The effects of E2 on proinflammatory responses to infection, in particular CCL2 responses, and disease outcome are primarily mediated by signaling through ERα." (PMID 21829352, 2011). "Only CXCL10 expression was significantly attenuated in TLR4 mutant mice at day 3 post-infection, whereas the majority of mediators, including CCL2, CXCL1, and IL-1β were similar between TLR4 mutant and WT mice across all time points examined." (PMID 21496301, 2011). "At this phase of infection before severity of disease, there was an increase in expression of various proinflammatory mediators also like Tnf-α, Il1α, Il1β, Il-12 and Ccl2/MIP-1α along with chemoattractants." (PMID 21371334, 2011). "We analyzed CCL-2 plasma levels in groups stratified on the basis of 1) remote (EC = 65) or recent (HC = 92) infection and 2) TST status in these groups." (PMID 21991356, 2011). "One such C-C chemokine CCL-2, is produced by activated T cells and macrophages and exclusively recruits monocytes and T cells to the site of infection in mycobacterial diseases." (PMID 21991356, 2011). "Previous study has demonstrated that the WNV-infection stimulated the expression of CCL2 in mice livers, suggesting a consistent result to our study of JEV." (PMID 21345237, 2011). "Our results showed that P3 infection enhanced the releases of IL-10 and CCL2 of DCs but suppressed the production of IFN-α and TNF-α." (PMID 21269456, 2011). "In contrast, CCL2 levels were significantly higher in both intact virus and transfected DNA treated corneas as compared to mock infection." (PMID 20419141, 2010). "Accordingly, experimental infection with L. braziliensis leads to increased leukocyte recruitment, CCL2 and CXCL10 expression, and production of IL-10." (PMID 20559550, 2010). "The elevated levels of Ccl2 and Cxcl-10 suggest recruitment and activation of dendritic cells, macrophages, neutrophills and other white cells to the sites of infection." (PMID 20062542, 2010). "Following infection significant increases of CCL2 (MCP-1), CCL3 (MIP-1α), CCL4 (MIP1-β), CCL5 (RANTES) and CXCL9 (MIG) were observed in WT NOD mice compared to uninfected controls." (PMID 19122812, 2009). "It is also established that JEV infection leads to massive upregulation of inflammatory cytokine levels, and neurons also respond to infection by secreting CCL2, and type I and II IFNs." (PMID 19956550, 2009). "Infection of WT mice with rMA15 resulted in a significant induction of proinflammatory chemokines including CCL2 (MCP-1), CCL3 (MIP-1α), and CCL5 (RANTES) as compared to mock-infected control mice." (PMID 19079579, 2008). "Similarly, the CCL2 knockdown study involved the administration of siRNA 24 and 72 h after infection with the SARS-CoV-2 virus, which demonstrated efficacy in a model of already established disease." (PMID 41596367, 2026). "First, it could be hypothesized that patients with schizophrenia are more susceptible to infection because they have a greater inflammatory state, with the upregulation of adhesion molecules (ICAM-1, sP-selectin) and chemokines (such as CCL2)." (PMID 40276385, 2025). "The Ccl2 gene, strongly upregulated by 4T1 cancer cells, remained unaffected by infection." (PMID 40547518, 2025). "Studies of monocytes infected with Cpn have shown a significant increase in CCL2, suggesting infection may lead to a pro-inflammatory state." (PMID 40584180, 2025). "Additionally, increased MCP-1 (CCL2) levels were measured in the serum of Irgb6−/−Gbp4−/− mice compared to WT on day 7 post-infection." (PMID 40607809, 2025).
infection (continued). "Additionally, we uncovered the immunoregulatory properties of PB8, which modulates CCL2 serum levels, potentially reducing inflammation by limiting monocyte recruitment to the infection site." (PMID 41259559, 2025). "Notably, cytokine family members Ccl2, Ccl3, Ccl4, Ccl5, Ccl7, Ccl9, and Ccl22 were also significantly activated following infection." (PMID 40539063, 2025). "Neuroinflammation may be an outcome of infection with one or both organisms as observed by increased levels of CCL2 and IL-6 leading to AD pathogenesis." (PMID 40584180, 2025). "However, in both the previous and current studies, EV-D68 infection led to induction of MCP-1 (CCL2 in the mouse cytokine panel), suggesting that this cytokine is a common response to EV-D68 across tissue types." (PMID 40459936, 2025). "Additionally, the immune inflammatory response activated by SC infection results in high CCL2 expression, which attracts large numbers of CD45 + inflammatory cells to peripheral nerves, thereby exacerbating JEV-induced neurotoxicity." (PMID 40857326, 2025). "CCL2 levels were enriched in B cells of both subcutaneously and intravenously infected animals, while upregulation of CCL2 in ILCs and macrophages was significant only following subcutaneous infection." (PMID 40178612, 2025). "These two viruses are also known to induce CCL2 upon infection." (PMID 40996032, 2025). "CCL2 (MCP-1) attracts monocytes to the location of infection and inflammation." (PMID 41280310, 2025). "Notably, the group treated with SSO up to 2 h before infection had the lowest levels of inflammatory cytokines, including CCL2, a chemokine that promotes immune cell infiltration." (PMID 40137298, 2025). "This has many implications for increased neuroinflammation, especially during times of infection when CCL2 levels may be increased." (PMID 40584180, 2025). "In the striatum, we also see clustering within the fentanyl-treated groups based on infection status: EcoHIV-infected mice treated with fentanyl had higher concentrations of CCL2, CCL4, CCL5, and CCL11 but lower levels of CCL3 and CXCL10 than the uninfected, fentanyl-treated animals." (PMID 40447886, 2025). "In addition, CCL2 recruits monocytes, memory T cells, and dendritic cells in response to tissue injury or infection." (PMID 39852930, 2025). "Hypothetically, these chemokines may contribute to TB control by attracting monocytes to the site of infection via CCL2 and antigen-engaged B cells and central memory T cells via CCL19 and CCL21, respectively." (PMID 40458184, 2025). "To further explore the immunomodulatory properties of KYNA, we investigated its impact on the production of CCL-2, a chemokine critical for the recruitment of monocytes and macrophages to sites of infection, which is crucial in initiation and sustaining inflammatory response." (PMID 40807308, 2025). "However, by 12 hours after infection, the expression of Ccl2, Cxcl1, Cxcl9, and Cxcl10 in the dLN of WT CHIKV–infected WT mice, but not MARCO–/– mice, was significantly increased in comparison with mock-infected mice." (PMID 38194268, 2024). "For example, the chemokine CCL2 increases T. cruzi recruitment in vivo, which suggests a pre-existing inflammation may help regulate subsequent tissue infection." (PMID 39770386, 2024). "These shifts in CCC pathways were also reflected in single-cell level ligand activities, which showed increased predicted activity of IL1B at the time point of maximal perturbation in all animals but only an increase in CCL2 activity at 4 weeks post-infection in both 170-infected animals." (PMID 38317183, 2024). "CCL2 tightly regulates cellular mechanics and thereby recruits monocytes, memory T cells, and dendritic cells to the site of inflammation produced by either tissue injury or infection." (PMID 38786055, 2024).
infection (continued). "We hypothesised that the increase in expression of Cxcl12/Ccl2/Ccr2 signalling axis components in miR-126 knockdown embryos is responsible for the recruitment of macrophages to infection." (PMID 38307625, 2024). "Monocyte egress from the BM is dependent on CCR2, a receptor for CCL2, during infection." (PMID 39040105, 2024). "Therefore, the changes in the neuroimmune landscape between acute and chronic infection likely contribute to distinct cues and cell types producing CCL2 at different stages of the infection." (PMID 38206985, 2024). "In the WNV mouse model, CCL2 and CCL7 are important ligands for CCR2 and affect monocyte infiltration to the CNS; however, only CCL7 deficiency is associated with increased sensitivity to infection." (PMID 38997413, 2024). "We observed significantly decreased immune cell recruitment and increased parasite burden in the brain during chronic, but not acute, infection of mice deficient in astrocyte CCL2 production, without an effect on peripheral immune responses." (PMID 38206985, 2024). "MCP-1/CCL-2 is a chemokine that plays a major role in recruiting leukocytes, including monocytes, neutrophils, and lymphocytes, from the bloodstream across the vascular endothelium in response to infections or inflammations." (PMID 39567619, 2024). "A recent preprint study conducted by Kim and Colleagues suggested that CCL2 is required for the development of HAND during systemic EcoHIV infection of mice by promoting monocyte migration during the initial stages of infection, however, once HAND is established CCL2 is dispensable." (PMID 38282400, 2024). "To investigate this, we first assessed ccl2 and ccr2 transcript abundance after infection." (PMID 38307625, 2024). "The Ccl2 gene was upregulated 25.9-fold by Gm29156 at the acute infection stage." (PMID 38229193, 2024). "In addition, the TNF-α and CCL2 gene expression levels were significantly higher after infection with the Y. enterocolitica strain 1186C in comparison with the A. caviae strain 1185C." (PMID 38721607, 2024). "Furthermore, during acute infection, the alarmin s100a11 promotes a Ccl2-mediated monocyte recruitment to the site of infection." (PMID 39446964, 2024). "In addition, CCL2/MCP-1 levels are shown to be upregulated during the early phase of infection and increase significantly during the late stages of the disease in non-surviving patients." (PMID 39281667, 2024). "In our review, we found most frequently increased CCL2 (41.7% in vitro, 45.5% in vivo, and 33.3% in human serum during the acute phase of infection), CCL5 (50% in vitro, 38.6% in vivo), and CXCL10 (41.7% in vitro, 40.9% in vivo, and 33.3% in human serum during the acute phase of infection)." (PMID 38543749, 2024). "Importantly, an 18-fold reduction in CCL2 levels was identified in PARP-1 knockout mice in the setting of infection." (PMID 39201718, 2024). "Infection triggered an increase in neutrophil accumulation in the liver; these cells produced TNF-α (significantly higher in females after infection), CCL2, and CXCL1, and the percentage of neutrophils producing CXCL1 was significant higher in males and females compared to uninfected mice." (PMID 38179044, 2023). "Higher levels of Tnf, Cxcl1 and Ccl2 in Karp-infected MΦ were consistent with our in vivo results, showing the increased myeloid cell infiltration and activation in the lungs at early infection." (PMID 38091346, 2023). "Furthermore, significant variations were observed in the levels of IFNL1, IL1A, IL6, and CCL2 interferons or other cytokines in cell supernatant through ELISA when comparing these two infection conditions." (PMID 37515115, 2023). "Similarly, the expression levels of pro-inflammatory response factors (IL-6, TNF-α, CXCL10, CCL7, CXCL11, and CCL2) were significantly decreased at 6 dpi, as compared to virulent WT infection." (PMID 37623322, 2023). "Knockout of CCL2 or CCR2 significantly impaired BMM infection measured by EGFP expression." (PMID 37085605, 2023).
infection (continued). "As in humans, CCL2 was the most prominent CC chemokine produced during infection." (PMID 36851549, 2023). "However, in severe COVID-19 patients, the infection of alveolar epithelial cells by SARS-CoV-2 induces the production of chemokine CCL2, which attracts a large number of circulating monocytes and tissue-resident alveolar macrophages to the site of infection." (PMID 38005826, 2023). "In contrast, USUV infection induced significantly greater upregulation of CCL2 and IL1α." (PMID 36495563, 2023). "infection markedly increased CCL2 chemokine levels in the BALF." (PMID 37624851, 2023). "However, even though the general inflammatory response is more potent for WNV than for USUV, some chemokines such as CCL2 are more secreted by the hBBB upon USUV infection." (PMID 36495563, 2023). "Thus, the shutdown of CCL2 production at the transcriptional level would create a great deterrent to the infection of both macrophages and T cells by limiting the recruitment of susceptible cells." (PMID 38005838, 2023). "CCL2- and CCL2+ macrophages show nearly identical changes among the transcripts with the greatest increases in abundance with infection, and somewhat greater variability among transcripts with the greatest decreases in abundance with infection." (PMID 37318981, 2023). "Infection with virulent ASFV isolates often results in an exacerbated immune response, associated with elevated serum levels of pro-inflammatory cytokines (IL-1α, IL-1β, IL-6, TNF, CCL2, CCL5 and CXCL10)." (PMID 36680273, 2023). "CCL2/MCP-1 is a chemokine produced constitutively or in response to proinflammatory stimuli that is involved in the recruitment of monocytes, lymphocytes, and other cells to sites of infection and inflammation peripherally and in the CNS." (PMID 37651083, 2023). "However, CLEC2.Fc efficiently inhibited the expression of proinflammatory cytokines (IL‐6, TNF‐α, IFN‐γ, and IL‐10) and chemokines (CXCL1, CXCL2, CXCL5, CCL2, IP‐10) at day 3 and day 5 post‐infection (blue columns)." (PMID 37211986, 2023). "As expected, we found that CCL11 together with CCL2, CCL3, and the receptors CCR2, CCR3, and CCR5 were all upregulated in newly-weaned hamster brain tissues after Delta variant infection at 2, 4, and 7 dpi, of which CCL11 and CCR2 were significantly higher at 4 dpi." (PMID 37122119, 2023). "However, one set of type II ISGs was also upregulated in male-derived neutrophils following infection e.g. Casp1, CtsI, Ccl2." (PMID 38179044, 2023). "The examination of human cytokine levels revealed that while the levels at the primary site of infection were similar for huSGM3 and huNSG mice, strongly increased levels of CCL2, IL-6, IL-8 and TNF-α could be measured by the Luminex assay in the blood." (PMID 36969151, 2023). "Infection with the H7N7 resulted in increased levels of CCL2, IFNγ, IL1β, IL-6, and TNFα in the brains of mice, whether or not they had been previously vaccinated." (PMID 37063291, 2023). "Although the interaction between both pathogens plays an important role in the progression of both infections, there are still unknown mechanisms that may influence the pathogenicity of one or the other by increasing or decreasing CCL2 levels." (PMID 37999614, 2023). "Moreover, the infection suppressed mRNA expression of IL-8 (∼3-fold; p < 0.0001; p < 0.0001) and CCL2 (∼3-fold; p < 0.0001; p = 0.0002)." (PMID 36883057, 2023). "CCL2 is a chemokine which can attract a wide variety of immune cells (monocytes, macrophages, B and T cells, NK cells, neutrophils), usually produced after tissue injury/infection to promote the extravasation of effector cells to the selected site." (PMID 38130717, 2023). "Interestingly, CCL2 transcription was somewhat upregulated at late infection, whereas its protein release to the supernatant was decreased." (PMID 35019713, 2022).
infection (continued). "It is, therefore, conceivable that CCL-4, CCL-5, CXCL-10 and IL-8 would initiate and maintain the inflammatory response in the acute phase of infection and the increased release of CCL-2 during the convalescent phase would regulate the immune response in order to reduce immune pathologies." (PMID 35543881, 2022). "It is known that in infection, CCL2 recruits monocytes and enhances phagocytic properties." (PMID 35285058, 2022). "CCL2 was one of the most highly secreted cytokines in the early stages of infection." (PMID 36005818, 2022). "Infection with P. aeruginosa induced not only a significant increase in the transepithelial migration of THP-1 cells in the presence (seven-fold) but also in the absence (five-fold) of the monocyte chemoattractant CCL2." (PMID 35892600, 2022). "In contrast, infection with W83 only increased the AoSMC expression of Ccl2, Icam1, and Eng." (PMID 36483452, 2022). "Recruitment of monocytes to sites of inflammation, such as bacterial infection, is mediated by chemokine CCL2 (MCP-1) produced by MSC, which mobilizes release of inflammatory monocytes from bone marrow and recruitment to sites of high CCL2 production (i.e., infection)." (PMID 36356087, 2022). "Additionally, IL-8 and the chemokines CCL-2,5 are important for recruiting neutrophils, monocytes, and T lymphocytes at the site of infection." (PMID 36297190, 2022). "While clade V virus had fewer significantly differentially expressed genes, the major genes involved in cytokine storm; TNF pathway and neutrophil chemotaxis, Ccl2 and Ccl7 remained, suggesting similar, but milder presentation of pathology for its infection outcome." (PMID 36389747, 2022). "Astrocytes and neurons could produce CCL2 which is involved in monocyte recruitment and induces the reactivity of microglia during infection." (PMID 34399779, 2021). "However, an enhanced upregulation of 9 genes, all involved in the NF-kB pathway (CCL2/MCP1, CCL20, CCL4, CXCL2/MIP2α, IL1A, NFKBIA, PTX3, TNFA, TNFAIP3), was observed after infection with D26 variants, in comparison to the WT." (PMID 33399033, 2021). "In addition, infection with Δpmi slightly decreased the expression of Ccl7 and Ccl2 in RAW264.7 cells compared with WT infection." (PMID 34491082, 2021). "The B.1.351 infection resulted in a >25-fold increase in IL-6 and CCL2 mRNA expression." (PMID 35062231, 2021). "In this regard, we want to highlight the chemokine (C-C motif) ligand 2 (CCL2), a chemokine that is greatly over-expressed in response to oxidative stress and is responsible for the migration of monocytes to the infection zone and their differentiation into macrophages." (PMID 34205807, 2021). "In addition, CXCL1 and CCL2 in infected WT kidneys were described to be detectable as early as 12 h after infection, supporting rapid recruitment of innate myeloid cells." (PMID 33608410, 2021). "Therefore, negative regulation of the interferon pathway is operative in the Tpl2-/- mice, although delayed such that CCL2 protein levels are inefficiently suppressed at 9 dpi, potentiating cellular infiltration in Tpl2-/- mice late during infection." (PMID 34691044, 2021). "Infection led to increases in proinflammatory CCL2, IFNγ, IL6 and CXCL10 in wt mice." (PMID 34237114, 2021). "To further identify whether other chemokines besides KC/GRO were impacted by infection, we also examined the production of CCL2 and CCL3 by ELISA." (PMID 33878120, 2021). "Similarly, infection of monocyte-derived macrophages by SARS-CoV in vitro induces expression of CCL2/MCP-1 and CXCL10/IP-10 in an IFN-independent manner." (PMID 34239884, 2021). "Also, the monocyte chemoattractant molecule CCL-2, was found upregulated during the early phase of infection, further increased during late stages of fatal disease and associated with a prolonged duration of intensive care unit stay." (PMID 34473805, 2021).